CDK4 (cyclin dependent kinase 4)
Diseases named in the same sentence as CDK4 in open-access papers (continued):
Sharing a sentence is not in itself a finding about the gene and the disease.
cancer (continued). "The Vascular Endothelial Growth Factor Receptor 2 (VEGFR-2) and Cyclin-Dependent Kinase 4 (CDK4) are the most important therapeutic targets in cancer research because of their pivotal roles in cancer processes, angiogenesis, and uncontrolled proliferation, respectively." (PMID 41471388, 2025). "CDK4/6 inhibitors induce cell cycle arrest at the G1 phase in Rb-proficient cancer cells." (PMID 40563591, 2025). "Similarly, oxindole‐indole conjugates have been reported to selectively inhibit CDK4, demonstrating their potential for cell cycle arrest in cancer therapy." (PMID 41523619, 2025). "Furthermore, ongoing preclinical studies and early-phase clinical trials are dedicated to exploring the significant role of CDK4/6 inhibition in treating other cancer types." (PMID 40563591, 2025). "Specific inhibitors against CDK4/6 were recently introduced in cancer therapy." (PMID 40740245, 2025). "Remarkably, the mere activation of Wnt/ERK/CDK4/6 in E/M cells suffices to cement a programme integrating cancer stem cell maintenance (via FOXC2/p63) and self-renewal (via S-phase and FOXM1 activation) with inhibition of differentiation (via EGFR inactivation)." (PMID 40764669, 2025). "In accordance with these observations, CDK4/6 inhibitors have synergistic effects with autophagy inhibitors such as hydroxychloroquine, Lys05, CQ, bafilomycin A1 and spautin-1, leading to irreversible growth arrest in cancer cells." (PMID 41388212, 2025). "Constitutive activation of CDK4/6 represents a driving force in the onset of several cancer types." (PMID 40468178, 2025). "Notably, we find that CDK4/6 inhibitor resistant tumors exhibit immune suppressive cancer to myeloid signaling and hindered T cell recruitment and activation during treatment." (PMID 40032842, 2025). "First, by examining a cohort of patients with detailed treatment histories, we established that APOBEC3 mutagenesis is associated with shorter outcomes on targeted therapies, including antiestrogen monotherapy and antiestrogen plus CDK4/6i combinations among HR+ cancers." (PMID 40379787, 2025). "NETs with an activated CDK4/CDK6-phospho-RB1 pathway may be candidates for cancer therapy with CDK4/CDK6 inhibitors." (PMID 41375037, 2025). "Common activities shared by CDK4 and CDK6 in cancer have been mostly identified and confirmed evaluating the roles of CDK4 and CDK6 specific inhibitors and, among them the principal is indubitably to promote cell proliferation by directly phosphorylating RB and indirectly through mTORC1 activation." (PMID 39800748, 2025). "This suggests that overexpressing EMI1 cancers are likely to avoid CDK4/6 inhibition, leading to premature and under-licensed S phase entry, which may result in increased genome instability." (PMID 40244377, 2025). "In CDK4/6i-resistant cancer cells, CDK6 is often overexpressed." (PMID 40093074, 2025). "Additional mechanisms contributing to the increased immunogenicity of cancer cells treated with CDK4/6 inhibitors include the Rb-dependent activation of long terminal repeat (LTR) enhancers, which regulate genes involved in immune surveillance and antigen presentation." (PMID 41388212, 2025). "Therefore, exploring the broader applicability of CDK4/6 inhibitors in various cancers remains an area of unmet clinical need." (PMID 40593477, 2025). "As a selective CDK4/6 inhibitor, ribociclib delays cancer progression by inhibiting CDK4/6." (PMID 41438984, 2025).
cancer (continued). "While autophagy initially suppresses tumorigenesis by maintaining cellular homeostasis, it evolves into a pro-survival mechanism in advanced cancers, enabling resistance by reversing CDK4/6 inhibitor-induced G1 arrest through reactive oxygen species (ROS) scavenging and metabolic adaptation." (PMID 40421216, 2025). "CDK4/6 inhibition is a crucial therapy for targeting cell cycle dysregulation in cancer treatment." (PMID 40563591, 2025). "Finally, additional trials to follow on successful initial results are required in the case of appendiceal carcinomas with GNAS mutations and to further elucidate the mechanisms of sensitivity or resistance of these cancers to CDK4/6 inhibitors." (PMID 40699853, 2025). "The dependency of MYC-driven cancers on CDK4 presents opportunities also for synthetic lethality." (PMID 40076599, 2025). "Notably, CDK6 is often upregulated in CDK4/6i-resistant cancers and rapidly proliferating hematopoietic stem cells, underscoring its unique regulatory roles." (PMID 40093074, 2025). "By enhancing cyclin D1 degradation, it may be possible to sensitize cancer cells to CDK4/6 inhibitors, overcoming resistance and improving therapeutic outcomes." (PMID 40408472, 2025). "Multiple preclinical studies have suggested that the immunomodulatory effects of CDK4/6 inhibitors may enhance the efficacy of ICIs, thereby providing a rationale for combination therapies in cancer patients." (PMID 41388212, 2025). "In particular, the decreased proteasomal degradation of PD-L1 together with the activation of a Rb/NF-κB-mediated transcriptional network have been identified as molecular events mediating the up-regulation of PD-L1 in cancer cells upon treatment with CDK4/6 inhibitors." (PMID 41388212, 2025). "The CDK4/6-DUB3-YAP1 axis may represent a common regulatory mechanism with broader implications for the treatment of multiple cancers, warranting further investigation." (PMID 40307228, 2025). "Furthermore, recent data from the Malumbres laboratory showed that pretreatment of cancer cells with CDK4/6i rendered the cells resistant to chemotherapeutic drugs, whereas treatment after chemotherapy resulted in synergistic effects." (PMID 39788939, 2025). "Thus, CDK4/6 inhibitors have been recommended as promising targeted therapeutics for various cancers." (PMID 39000513, 2024). "Cell cycle arrest in cancer cells can be achieved by pharmacologically inhibiting CDK4 and CDK6." (PMID 39196911, 2024). "A retrospective chart review of patients with HR+, HER2-negative metastatic BC conducted at a cancer center in Washington reported that the CDK4/6 inhibitor palbociclib was prescribed most frequently in combination of with the aromatase inhibitor letrozole (73.5%)." (PMID 38997691, 2024). "Furthermore, we recently showed that endocrine therapy and CDK4/6 inhibitors commonly increase ROS levels in cancer cells and lead to cAMP-induced DNA damage, leading to PARP trapping and transcriptional blockage." (PMID 38879508, 2024). "Inhibiting the cyclin D1 and CDK4/6 complex can induce G1 phase arrest in cancer cells." (PMID 38338430, 2024). "The identification of biomarkers could have wider implications and be especially useful, given the current efforts being made to test the efficacy of CDK4/6is in other types of cancers." (PMID 38831405, 2024). "Moreover, their insensitivity to CDK4/6i indicates the primacy of CDK2 in driving the G1 to S transition in CCNE1-amplified cancer cells." (PMID 38047585, 2024). "Thus, the non‐cell‐specific nature of CDK4/6i implies their potential interference not only with the cell cycle of cancer cells but also with other cells, such as neural precursor cells in hippocampus, which are pivotal for neurogenesis." (PMID 39009505, 2024). "Significant difference between cancer and normal tissues was also seen for CDK4 and pRb." (PMID 38963708, 2024). "CDK4/6i effectively block cancer cell proliferation by inducing G1 cell cycle arrest." (PMID 39156700, 2024).
cancer (continued). "Additionally, the impact of this peptide on the cancer cell cycle and migration was evaluated, and ultimately, the expression of cyclin-dependent kinase 4/6 (CDK4/6) genes was investigated." (PMID 38866982, 2024). "Furthermore, the peptide exhibited the ability to halt the progression of cancer cells in the G1 phase of the cell cycle and impede their migration by suppressing the expression of CDK4/6 genes." (PMID 38866982, 2024). "It was the first inhibitor of CDK4/6 approved for cancer treatment." (PMID 39495719, 2024). "In the present study, although the extent of senescence elicited by DNA‐damaging agents and CDK4/6i was similar, CDK4/6i‐induced senescent cancer cells showed significantly lower expression of well‐known pro‐inflammatory SASP such as IL‐6, CXCL1, CXCL8, and TGF‐β." (PMID 37854019, 2024). "CDK4/6 inhibitors block cancer cell proliferation by inducing cell cycle arrest at G1." (PMID 38344066, 2024). "Thus, our results provide intriguing cellular evidence pointing to MYC as an attractive target for preventing or overcoming CDK4/6i resistance in cancer cells." (PMID 38424044, 2024). "Several clinical trials are now ongoing investigating CDK4/6 inhibitors in paediatric cancers." (PMID 41146951, 2024). "Additionally, andrographolide was found to augment the production of tumour necrosis factor-alpha and the expression of CDK4 marker, boosting lymphocyte cytotoxicity against cancer cells indirectly." (PMID 39583105, 2024). "CDK4/6 activity is required for G1 progression in many other cell types, implying that these drugs may also benefit a wider range of cancers." (PMID 38438376, 2024). "Moreover, we identified a MYC-degrading molecule, A80.2HCl, that efficiently reduces MYC protein levels and overcomes CDK4/6i resistance, shedding light on strategies for the expanded use of CDK4/6i in cancer treatment." (PMID 38424044, 2024). "Pharmacological inhibition of CDK4/6 has emerged as a promising anti‐cancer strategy." (PMID 36453028, 2024). "Ultimately, our findings may provide a novel strategy for patients with HPV− HNSCC by cotargeting mTOR and key cell cycle–regulating molecules, which can also have an impact in multiple cancer types that fail to respond to CDK4/6 inhibitors as single agents." (PMID 38954773, 2024). "RB1 is essential for CDK4 inhibitors to inhibit cancer cell proliferation." (PMID 39351198, 2024). "We demonstrated that CDK4/6 inhibitors stabilized TSC1 in cancer cells." (PMID 38890443, 2024). "Cyclin-dependent kinase 4/6 (CDK4/6)-cyclin D axis is deregulated in various cancer types." (PMID 38170401, 2024). "In light of the role of CDK4/6is in increasing PD-L1 expression, there is potential for combining CDK4/6is with the PD-1/PD-L1 immune checkpoint blockade to improve therapeutic effectiveness in cancer treatment." (PMID 39593745, 2024). "Importantly, CDK4/6 inhibitor therapy plus anti-PD-1 immunotherapy significantly boosts tumor shrinkage and substantially enhances survival rates in mouse models of cancer." (PMID 38638430, 2024). "Consequently, CDKL3 can assist the cell cycle progression and cell proliferation in cancer via dual paths — CDK4 stabilization and Rb phosphorylation in parallel." (PMID 38963708, 2024). "Besides cell-cycle arrest, there is growing evidence that CDK4/6is exert paradoxical roles on cancer treatment by altering the immune system." (PMID 39593745, 2024). "Previous studies indicated that CDK4/6 inhibitors could induce cell cycle arrest and increase the ferroptosis sensitivity of cancer cells through lipid metabolic process disruption." (PMID 39362848, 2024). "However, a large number of patients present disease progression due to cancer cells resisting CDK4/6 inhibitors." (PMID 38540112, 2024). "We sought to investigate how a CDK4/6 inhibitor modulates the expression of TSC1 in cancer cells." (PMID 38890443, 2024). "CDK4/6 are considered key targets for cancer drug development." (PMID 39518013, 2024).
cancer (continued). "However, most patients will eventually present disease progression, suggesting that cancer cells resist CDK4/6 inhibitors." (PMID 38540112, 2024). "Moreover, CDK4/6 inhibitors, which mimic the function of p16, have been demonstrated to induce senescence in various cancer cells, reducing the proliferative capacity of activated T cells while preserving their cytotoxic efficacy." (PMID 38750022, 2024). "Therefore, further in-depth examination of combined therapy with ICIs and CDK4/6 inhibitors in pan-cancer patients with CDKN2A ALT will be necessary in future studies." (PMID 38822443, 2024). "Activation of p16 leads to the inhibition of the cyclin-dependent kinases CDK4/6 and CDK2, which play a vital role in cell cycle regulation and are implicated in various physiological processes like cancer, tissue regeneration, aging, cellular senescence, and development." (PMID 38686050, 2024). "Thus, targeting the abnormally activated CDK4/6–cyclin D1 complex has been demonstrated to be a promising therapeutic approach against some cancers." (PMID 39593745, 2024). "This lipid checkpoint is likely generally used by non-transformed cells while many cancer cells have lost the G1 lipid checkpoint because of mutated Rb, p21, or upregulated CDK4/6 activity." (PMID 38499565, 2024). "We have shown that increased activation of the PI3K/AKT/mTOR signalling axis in samples collected from MBC patients that develop disease progression when treated with a CDK4/6 inhibitor in combination with ET extends beyond cancer cells into the surrounding stroma/immune compartment." (PMID 39322687, 2024). "In this review, we comprehensively discuss the paradoxical immunological effects of CDK4/6is in cancer treatment, elucidating their anticancer mechanisms through immunomodulatory activity and induction of acquired drug resistance by dysregulating the immune microenvironment." (PMID 39593745, 2024). "Thus, our data suggest that high MYC expression drives resistance to CDK4/6i by reducing pRB1 protein abundance in cancer cells." (PMID 38424044, 2024). "The complex regulatory responses of cancer cells to CDKN2A inactivation may account for the development of resistance in cancer cells to CDK4 inhibitors." (PMID 39351198, 2024). "The overexpression of CDK4/6 due to genomic alterations is common in most human cancers." (PMID 38338430, 2024). "The dysregulation of CDK4 in multiple pathways leads to the uncontrolled growth of cancer cells." (PMID 39159071, 2024). "Although P16 is an endogenous CDK4 inhibitor, only a few primary cancers with P16 inactivation may be sensitive to treatment with CDK4 inhibitors." (PMID 39351198, 2024). "In addition, degradation of CDK4/6 also eliminates other functions of CDK4/6 besides kinase activity, which benefits cancer therapy." (PMID 38138549, 2023). "Interestingly, recent studies in melanoma suggested that CDK4/6 inhibitors also exhibited complementary immunotherapeutic activity for cancer treatment." (PMID 37631380, 2023). "We selected BNC105, a microtubule-binding drug used as a vascular targeting agent for cancer, and Palbociclib, a CDK4/6 inhibitor approved for cancer therapy, and compared the cell-killing efficiency of these substances to that of Bortezomib, either alone or in combination." (PMID 37111759, 2023). "Our in vitro results showed that CDK4 inhibitors could simultaneously inhibit the cell viability of both cancer cells and P-Tex cells." (PMID 36811599, 2023). "Using the CDK4/6 inhibitorribociclib as a prototype, we identified a covalent handle that, whenappended to the exit vector of ribociclib, induced the proteasome-mediateddegradation of CDK4 in cancer cells." (PMID 37252349, 2023).
cancer (continued). "It should be noted that, according to the information reported by the cBioPortal for cancer genomics, the human RB1 gene, as well as the genes encoding CDK4 (CDK4), CDK6 (CDK6), and cyclin D1 (CCND1), are all expressed in AGS and MCF-7 cells, without mutations reported so far." (PMID 37298236, 2023). "Therefore, the CDK4/6 inhibitors effectively block the proliferation of sensitive cancer cells by arresting the G1 cell cycle." (PMID 37759823, 2023). "Theoretically, it would be predicted that many human cancers will show increased CDK4/6 reliance and make ideal candidates for CDK4/6 inhibitor treatment since they often activate CDK4/6 genes or have transcriptional aberrations through a variety of mechanisms." (PMID 37240281, 2023). "The full potential of CDK4/6i is yet to be known, with many trials ongoing to expand their utility to other breast cancer subtypes, such as early breast cancer, and even to other cancers." (PMID 36900131, 2023). "By virtue of their higher concentration and specific activity, they would have a greater effect of inhibition of PKM2 when they interact with SDPTEA, than happens when cancer cells avoid apoptosis, by using the NK region within the external loop in the C‐terminus of Cdk4." (PMID 37279947, 2023). "Interestingly, upregulation of CDK1 and CDK4 is correlated with poor prognosis in cancer patients, especially in those with resistance to 5-FU46–48." (PMID 37328457, 2023). "We then provided an introduction to CDK4/6 inhibitors and their use in cancer treatment." (PMID 37686364, 2023). "Overactivation of CDK2 activity may limit the potency of CDK4/6 inhibitors, and individual cancer cells with high cyclin E1 levels may increase CDK2 activity thus bypassing CDK4/6 blockade." (PMID 37369022, 2023). "For instance, CDK4 and CDK6 are frequently activated in human cancer, either by overexpression of their activating subunits, D-type cyclins, or inactivation of CDK4/6 inhibitors of the INK4 protein family, and they play an essential role in cell cycle entry and G1 progression." (PMID 36835173, 2023). "Therefore, cyclins and CDKs have been widely studied and targeted in cancer treatment, with four CDK4/6 inhibitors being approved by the FDA and many other inhibitors being examined in clinical trials." (PMID 37626854, 2023). "Overall the genomic landscape was stable, with pathogenic or likely pathogenic alterations being identified in 51 cancer genes, with 9 (18%) of them showing alterations being recurrent across different samples (MYCN, CDKN2A/2B, CDK4, GLI1, AKT1, IGF2, MED12, NCOR2)." (PMID 37730754, 2023). "The fact that CDK4/6 expression levels are substantially elevated in several cancers is well known." (PMID 36768557, 2023). "For example, CDK4/6 inhibitors were initially envisioned to (a) protect bone marrow cells (not necessarily all types of normal cells) (b) from chemotherapy with S-phase-specific drugs such as 5-fluorouracil and carboplatin (c) in patients with Rb1-negative cancers (resistant to CDK4/6 inhibitors)." (PMID 36913303, 2023). "Given that most driver mutations in cancer upregulate mitogenic signaling, which stabilizes c-Myc expression, cancer cells are likely more resistant to CDK4/6i than non-transformed cells." (PMID 38030655, 2023). "Therefore, the function of CKMT1 to phosphorylate CDK4 is a function different from creatine kinase, and it is important for cancer metabolism." (PMID 37061730, 2023). "The therapeutic benefits of CDK4/6 inhibitors extend beyond their use in cancer treatment." (PMID 37686364, 2023). "However, another study found that CDK4/6 inhibitors suppress anticancer immunity by upregulating PD-L1 expression and facilitating cancer immune evasion." (PMID 36871040, 2023).